RNU6-464P (RNA, U6 small nuclear 464, pseudogene)
Gene: Small nuclear RNA gene on chromosome 6 (53,153,795 to 53,153,898, reverse strand). Ensembl gene ENSG00000253026.
Homologues: Orthologues: macaque U6 (89% identical), mouse Gm26066 (73% identical), pig U6 (62% identical). Paralogues in human: RNU6-1060P (85% identical), RNU6-196P (84% identical), RNU6-41P (84% identical), RNU6-1152P (83% identical), RNU6-166P (83% identical), RNU6-20P (83% identical), RNU6-211P (83% identical), RNU6-35P (83% identical), RNU6-44P (83% identical), RNU6-748P (83% identical), RNU6-1042P (82% identical), RNU6-1145P (82% identical), and 1287 more.